WEE1 (WEE1 G2 checkpoint kinase)
Diseases named in the same sentence as WEE1 in open-access papers (continued):
Sharing a sentence is not in itself a finding about the gene and the disease.
cancer (continued). "Further suppression of Wee1 not only causes cell cycle arrest and inhibits the proliferation of cancer cells but also enhances CML cell sensitivity to Imatinib in vitro and in vivo, possibly through an excessive accumulation of overall DSBs." (PMID 36575478, 2022). "For example, WEE1 G2 checkpoint kinase (WEE1) inhibition in H3K36me3-deficient tumors can kill cancer cells via synthetic lethality." (PMID 34715919, 2021). "Cancer cells with SETD2 deficiency or mutations are more sensitive to WEE1 inhibitor Adavosertib, AKT-specific inhibitor, and PI3Kβ-specific inhibitors." (PMID 34715919, 2021). "In normal cells, the main function of WEE1 is to prevent replication of cells with DNA damage, however, in cancer cells, WEE1 has been linked to sustaining a tolerable level of genomic instability that favors tumor growth." (PMID 34277427, 2021). "Elevated WEE1 has been reported to be associated with tumor progression and poor disease-free survival in some cancers." (PMID 33986660, 2021). "FOXM1, E2F1, and WEE1 have been implicated in the pathogenesis of human cancers, yet their roles remain vague in STS." (PMID 33564073, 2021). "Recently, H3K36me3-deficient cancers can be selectively targeted by inhibition of WEE1, a cell cycle controlling kinase." (PMID 33260897, 2020). "Depending on the cancer subtype, the expression of WEE1 and PKMYT1 has been linked with the activation of cellular pathways crucial for the specific disease." (PMID 32958072, 2020). "Some of them, focused on the G2/M DNA damage checkpoint (e.g., PLK1, WEE1 G2 checkpoint kinase (WEE1) or telangiectasia mutated kinase (ATM)) are being investigated clinically in many cancers with promising results." (PMID 32268485, 2020). "Minor progress has been made via high-throughput drug screens in several tumors including cyclin-dependent kinase 1/2 (CDK1/2)-, polo-like kinase 1 (PLK1)-, and WEE1-mutated cancers." (PMID 32883316, 2020). "Wee1 inhibition caused induction of DNA damage during S-phase followed by mitotic failure in (pre)cancer cells." (PMID 32047167, 2020).
cancer (continued). "Inhibitors of WEE1 delay mitosis in several types of cancer and make cancer cells more susceptible to chemotherapy by inducing mitotic catastrophes." (PMID 31412533, 2019). "In accordance with the findings described here, it was demonstrated that H3K36me3-deficient human cancers are synthetic lethal with the WEE1 inhibitor AZD1775 as a result of dNTP starvation." (PMID 30674555, 2019). "Because cancer cells are more reliant on the G2/M checkpoint for DNA repair than normal cells due to G1/S DNA repair deficiencies, Wee1 inhibition can halt progression through the G2/M checkpoint and selectively induce apoptosis in cancer cells." (PMID 31921698, 2019). "Expression of proteins including CHEK1, CHEK2, ERCC1, ERCC2, PARP and WEE1 predispose cancer cells treated with chemotherapy toward DNA repair and proliferation." (PMID 35582583, 2019). "As WEE1 has been previously associated with many cancer types including CMM31,32, we wanted to further investigate the functional role of WEE1." (PMID 31506424, 2019). "In the light of mechanisms underlying Wee1 inhibition's anticancer actions, Wee1 blockade combined with DNA-damaging agents has been recently proposed in the treatment of cancer." (PMID 29977914, 2018). "Prior work has demonstrated that ectopic high-expression of WEE1 has been identified in several malignant tumors and associated with poor outcome, such as glioblastoma, vulvar squamous cell carcinoma, ovarian carcinoma, melanoma, and colorectal carcinoma." (PMID 30323762, 2018). "Another study showed that the WEE1 inhibitor selectively kills H3K36-deficient cancers through dNTP starvation resulting from ribonucleotide reductase subunit M2 depletion." (PMID 28852847, 2017). "The decrease or loss of miR‐15b expression and the overexpression of Wee1 have been related to invasive growth or tumour stages in several human cancers." (PMID 28145098, 2017). "Here we describe the targeting of H3K36me3-deficient cancers by exploiting a synthetic lethal interaction with WEE1 inhibition." (PMID 26602815, 2015). "With four different approaches, we demonstrate that H3K36me3-deficient cancer cells are hypersensitive to WEE1 inhibition." (PMID 26602815, 2015). "This supposition is supported by the fact that (excluding hyper-mutated tumors) there are no occurrences of tumors with mutations in both RAD17 and either CHEK1, CHEK2 and WEE1 across all cancer types in TCGA." (PMID 26437225, 2015). "Here we identify a synthetic lethal interaction in which H3K36me3-deficient cancers are acutely sensitive to WEE1 inhibition." (PMID 26602815, 2015). "This high prevalence of H3K36me3 loss further supports the medical intervention of treating H3K36me3-deficient cancers with the WEE1 inhibitor AZD1775." (PMID 26602815, 2015). "show that WEE1 inhibition selectively kills H3K36me3-deficient cancer cells through dNTP starvation resulting from RRM2 depletion." (PMID 26602815, 2015). "PTEN-deficient cancer cells often exhibit increased sensitivity to WEE1 inhibitors." (PMID 40565165, 2025). "Additionally, WEE1 inhibitors also demonstrate synergistic effects with various targeted therapies in KRAS-mutated cancers." (PMID 40885709, 2025). "H3K36me3-deficient cancers are hypersensitive to WEE1 inhibition." (PMID 40565165, 2025).
cancer (continued). "Other research by Lindemann and colleagues suggested that DNA aberrations and RS, caused by WEE1 inhibition, could be useful for cancer treatment under conditions of DNA repair disorder." (PMID 38279263, 2024). "In addition, the latest research reports that sirtuin 1 (SIRT1) deficiency induces WEE1 hyperacetylation and activation, rendering cancer cells resistant to WEE1 inhibition." (PMID 38231277, 2024). "WEE1 deficiency in cancer cells leads to hyperactivation of CDK1 and CDK2, thereby leading to multiple initiation of replication origins that causes depletion of replication factors, subsequent fork slowing, accumulation of single-stranded DNA and genomic instability followed by accumulation of RPA." (PMID 38279263, 2024). "Additionally, preclinical studies of WEE1 inhibition with adavosertib (also known as AZD1775) have demonstrated a synthetic lethal effect in SETD2-deficient cancers in cell lines." (PMID 38920407, 2024). "As a means to tolerate replication stress (by chemotherapy, radiation, oncogenes) and limit excessive genomic instability, WEE1 is commonly over-expressed by malignant cells and its high expression has been associated with poor rates of survival in various cancer types." (PMID 37715172, 2023). "Furthermore, Wee1 inhibition prolongs mitosis in a range of cancer cells and makes them more susceptible to chemotherapy-induced mitotic catastrophe." (PMID 38125947, 2023). "Moreover, WEE1 is associated with cancer progression and highly expressed in breast cancer, lung cancer, head and neck cancer, and ovarian cancer." (PMID 38143493, 2023). "Cancer cells very frequently harbour G1 checkpoint deficiencies and Wee1 inhibitor-mediated prevention of DNA repair following radiotherapy may lead to premature entry into mitosis and, ultimately, cell death via mitotic catastrophe." (PMID 36106115, 2022). "HuR was implicated with DNA-damaging anti-cancer agents by the acute upregulation of WEE1." (PMID 34572861, 2021). "Finally, acquired resistance to WEE1 inhibition by adavosertib has been linked to up-regulation of MYT1 in cancer cells." (PMID 33672884, 2021). "Importantly, the SETD8C302R mutation significantly increases the sensitivity of cancer cells to WEE1 inhibition." (PMID 33042742, 2020).
cancer (continued). "Thus, our study provides a rationale for using G2/M checkpoint inhibitors such as WEE1 inhibitors to target not only TSC2-deficient cells but cancer cells with hyperactivation of the mTORC1 pathway." (PMID 30266942, 2018). "Taken together, this creates a complex picture where either abnormal low expression, or high expression, of ATR, Chk1, or Wee1 in cancer cells may potentially cause increased sensitivity to inhibitors of these checkpoint kinases." (PMID 25774168, 2015). "We hypothesized that cancer cells would be susceptible to loss of Wee1 kinase activity based on the premise that all metazoan cells, including those in neoplasms, rely on the correct timing of cell cycle events for their survival and proliferation." (PMID 24927813, 2014). "WEE1 over expression is associated with several types of cancer." (PMID 24661910, 2014). "On the other hand, inhibition of CHK1/WEE1 halts the progression of the cell cycle, causing DNA damage and premature entry of the cell into the M phase, which may trigger selective destruction of cancer cells." (PMID 38606093, 2024). "Thus, compared to normal cells, these cancers could be particularly susceptible to G2/M checkpoint-targeted therapies, such as WEE1 or CHK1 inhibitors." (PMID 37987002, 2023). "On the other hand, knockdown of ATR, CHK1 or WEE1 by siRNA or inhibition of them by using specific inhibitors causes re-firing of DNA replication and thus further enhance replicative stress and lead to more DNA damage, which eventually causes cancer cell death." (PMID 28262781, 2017). "This lead us to hypothesize that, during prolonged mitosis in AMCDs-treated cancer cells, progressive Fcp1-induced Wee1 reactivation might lead to progressive loss of Cdk1 activity that weakens the SAC to a point in which the mitotic state could not be sustained." (PMID 27670139, 2016). "However, Wee1 may be downregulated through other mechanisms such as cancer-associated expression of microRNAs." (PMID 25774168, 2015). "As cancer cells including H1299 and HeLa are already highly aneuploid, they are likely to be relatively tolerant to some degree of DNA damage or chromosomal instability associated with the acceleration of cell cycle caused by partial inhibition of WEE1 pathway." (PMID 25301733, 2014). "The G1 checkpoint is dysregulated in many cancers, so inhibiting the WEE1 kinase activity is considered a promising therapeutic strategy due to its crucial role in regulating the G2-M checkpoint." (PMID 41286306, 2025). "WEE1-CAR T cells employ a multifaceted strategy in cancer therapy by inhibiting cell proliferation, triggering apoptosis, inducing cell cycle arrest, and suppressing key survival genes." (PMID 39820427, 2025). "This study is the first to investigate increased expression of WEE1 in multiple cancer types, including CML." (PMID 40893386, 2025). "These PD changes suggest that dual inhibition of KRASG12C and WEE1 are driving DNA damage and RS through independent but complementary mechanisms to further increase cancer cell death via apoptosis." (PMID 39807828, 2025). "Inhibitors of WEE1 (a serine/threonine kinase regulating the G2/M checkpoint) like Adavosertib (AZD1775) have been shown to overcome increased G2/M blocks occurring in cancer cells to counteract DNA damage." (PMID 40650150, 2025).
cancer (continued). "For tumors with low SLFN11 expression, systematically evaluate the efficacy of the combination regimens of ATR inhibitors, ATM inhibitors, CHK1 inhibitors, and WEE1 inhibitors with standard chemotherapy in different cancers." (PMID 40766331, 2025). "The use of WEE1i in cancer therapy blocks cancer cells from using WEE1 for DNA damage repair, and cancer cells enter mitosis prematurely, increasing DNA DSBs and ultimately leading to cancer cell death." (PMID 40240755, 2025). "Early clinical trials using WEE1 inhibitors in other cancers show promising results, highlighting the potential of this strategy." (PMID 39820427, 2025). "Herein, we have covered the possible strategies to address these barriers in depth, including insights drawn from WEE1 inhibition studies in other cancers." (PMID 40565165, 2025). "Alsterpaullone, Avotaciclib, Fostamatinib, and Naringin demonstrated acceptable inhibitory effects on both CDK1 and WEE1 proteins, suggesting potential for synergistic control of cancer cell proliferation." (PMID 41009727, 2025). "WEE1 (WEE1 G2 checkpoint kinase) expression facilitates cell cycle progression, while its inhibition suppresses cancer cell proliferation both in vitro and in vivo." (PMID 41246267, 2025). "Adavosertib is a well-known Wee1 inhibitor that has been used to inhibit G2/M transition in many other cancers as well as HGSOC." (PMID 39851561, 2025). "Wee1 inhibition by AZD1775 has been shown to cause increased DNA damage and induction of apoptosis in a variety of cancers." (PMID 39528354, 2025). "This orthogonal approach validates the key role of WEE1 in maintaining cell viability in this cancer type." (PMID 39807828, 2025). "Inhibitors targeting PLK1 or WEE1 are emerging as promising therapeutic agents for cancer treatment that disrupt the critical G2/M checkpoint, leading to cancer cell death." (PMID 39994376, 2025). "The WEE1 inhibitor (WEE1i) Adavosertib (AZD1775) has demonstrated preclinical efficacy in multiple cancer types, including paediatric solid tumours, pancreatic, and lung cancers, both as monotherapy or in combination with the standard of care." (PMID 41561634, 2025). "In conclusion, we demonstrated that FLNA regulates Wee1 expression by promoting its degradation, suggesting that low FLNA typical of ACC leads to increased Wee1 with consequent cancer cells growth." (PMID 39528354, 2025). "Numerous studies have explored the combination of WEE1 inhibitors with antimetabolites, like gemcitabine, in cancers, including pancreatic cancer." (PMID 40565165, 2025). "Moreover several other studies have shown that high levels of WEE1 expression are associated with worse prognostic factors, including metastasis, increased proliferative biomarkers, and resistance to treatment, in other cancers including glioblastoma, glioma, gastric cancer, and malignant melanoma." (PMID 40565165, 2025). "Previous research suggests that WEE1 inhibitors promote the premature entry of cancer cells into mitosis, but delay their exit, resulting in mitotic arrest and apoptosis." (PMID 38169513, 2024). "Reducing the expression of the G2/M checkpoint kinase Wee-1 (Wee1) in AML cells is an important target mechanism to mitigate cancer resistance and DNA repair." (PMID 38535455, 2024). "Results from preclinical studies in other cancer modalities support the effect of WEE1 inhibition on HR, and thus the assumption that WEE1 inhibitors, in combination with a DNA damaging agent, specifically render HRP cell lines more susceptible to treatment." (PMID 38894867, 2024). "These investigations have also identified four potential EGCG target proteins linked to cancer development: IKBKB, KRAS, WEE1, and NTRK1." (PMID 38978121, 2024).